IGF1 (insulin like growth factor 1)
Diseases named in the same sentence as IGF1 in open-access papers (continued):
Sharing a sentence is not in itself a finding about the gene and the disease.
sarcopenia (continued). "The supplementation of growth hormone (GH) and insulin-like growth factor-1 (IGF-1) seems to improve sarcopenia." (PMID 35052859, 2022). "While early-life reductions in circulating IGF-1 do lead to increased lifespan, reduced IGF-1 in advanced age has multiple consequences in animal models as it increases sarcopenia, bone frailty, learning and memory deficits, and cerebrovascular dysfunction." (PMID 34887742, 2021). "As blood biomarkers have been shown to be associated with the development of sarcopenia, this study will measure common blood biomarkers of IL-6, TNF-α, CRP, GH, IGF-1, and MSTN and FST as outcome measures." (PMID 34348792, 2021). "In a previous study, cellular interleukin-6 production and serum insulin-like growth factor-1 levels were significant predictors of sarcopenia, suggesting that they play an important role as inflammatory cytokines." (PMID 33855037, 2021). "The M.C treatment alleviated cisplatin-induced sarcopenia by stimulating IGF-1 towards M2 macrophage." (PMID 33804803, 2021). "In another cross-sectional study, it was found that women over 60 years of age with hip fractures had a high incidence of sarcopenia, and low serum IGF-1 and insulin-like growth factor binding protein-3 were detected in these women." (PMID 34650980, 2021). "Reduced exercise, lack of dietary intake, decreased type 2 muscle fibers in the skeletal muscle, and decreased secretion of insulin-like growth factor-1 (IGF-1) contribute to the development of sarcopenia." (PMID 34290624, 2021). "The apparent discrepancy between low IGF-1 signaling and high mTORC1 activation in aged muscle suggests an independent contribution of IGF-1 and mTORC1 signaling in sarcopenia." (PMID 32982690, 2020). "The prevalence of sarcopenia and slow gait speed significantly increased stepwise with a reduction in the IGF-1 level (p < 0.001 and p = 0.003, respectively)." (PMID 33050430, 2020). "The purpose of the study is to understand the factors associated with sarcopenia and the role of growth hormone (GH) and insulin-like growth factor (IGF-1) in the occurrence of sarcopenia." (PMID 32264885, 2020). "It is probable that this long persisting IGF-1 reduction will contribute to late effects, such as impaired growth, sarcopenia, endocrine disorders, metabolic syndrome and frailty seen in long-term survivors, and should be addressed in follow-up studies." (PMID 32793242, 2020). "The present study is the first to focus on the relationship between baseline serum BCAA/IGF-1 levels and sarcopenia/physical performance in patients with LC." (PMID 33050430, 2020). "Using the optimal BCAA and IGF-1 cutoff values for predicting sarcopenia (372 μmol/L and 48.5 ng/mL, respectively), the sensitivity and specificity were 0.709 and 0.759 for BCAA and 0.636 and 0.715 for IGF-1, respectively." (PMID 33050430, 2020). "Specifically, resistance training in patients with sarcopenia in liver cirrhosis prevents muscle breakdown and maintains physical function through its role in upregulating IGF-1." (PMID 32731496, 2020). "In parallel, age-related decreases in growth hormone [GH] and insulin-like growth factor-1 (IGF-1) levels are related to reduced muscle mass and function leading to poor physical performance and sarcopenia." (PMID 31947528, 2020). "The following five variables showed a significant relationship with sarcopenia in the univariate analysis: age, BMI, albumin, IGF-1, and BCAA." (PMID 33050430, 2020). "An ROC curve analysis was performed to determine the optimal cutoff values of BCAA and IGF-1, distinguishing between sarcopenia and non-sarcopenia." (PMID 33050430, 2020). "The prevalence of sarcopenia and slow gait speed significantly increased stepwise with a reduction in the IGF-1 level." (PMID 33050430, 2020).
sarcopenia (continued). "In this direction, the evaluation of sarcopenia represents the most promising tool, whereas laboratory biomarkers (such as p16INK4a, myostatin and Insulin-like Growth Factor 1) are still at a very experimental stage." (PMID 33114320, 2020). "The ensuing chronic inflammation can induce anabolic resistance in muscle, resulting in sarcopenia due to reduced insulin-like growth factor 1 (IGF-1) production and signaling that are essential for muscle regeneration and maintenance." (PMID 33139628, 2020). "To further develop these findings in the present study, we investigated the association between BCAA, IGF-1, and sarcopenia in more detail and evaluated the diagnostic performance of BCAA and IGF-1 for sarcopenia in patients with LC." (PMID 33050430, 2020). "In line with this, low levels of IGF-1 reduce mTOR activation of muscle protein synthesis, further contributing to sarcopenia." (PMID 32731496, 2020). "Sarcopenia is characterized also by a decline of the growth hormone (GH) and the insulin-like growth factor 1 (IGF-1)." (PMID 31457015, 2019). "IGF-1 treatment reduced histological hepatic steatosis, serum ALT and reversed the development of sarcopenia associated with NAFLD." (PMID 29724029, 2018). "HFD + GH and HFD + IGF-1 evidenced a significant reversion of sarcopenia at muscle structure level (fibre diameter) and significantly greater strength measurements than HFD assessed by ex vivo measurements through electromyography and in vivo assays." (PMID 29724029, 2018). "In conclusion, the supplementation of the somatotropic axis in a murine model of HGNA normalized aminotransferases, reversed sarcopenia and reduced hepatic triglycerides (mainly GH supplementation) and steatosis (IGF-1 supplementation)." (PMID 29724029, 2018). "Conversely, serum IGF-1 levels were lower in the sarcopenia group (58.16 ± 3.37 versus 72.61 ± 5.49, p = 0.039)." (PMID 29872072, 2018). "The improvement of sarcopenia by ghrelin can be attributed to the activation of the GH/ IGF-1 system." (PMID 30619872, 2018). "Growth hormone (GH) and insulin-like growth factor-1 (IGF-1) is another potential link between sarcopenia and NAFLD." (PMID 29673321, 2018). "Interleukin 6, secreted protein acidic and rich in cysteine, macrophage migration inhibitory factor, and insulin-like growth factor 1 levels differed significantly between the normal and sarcopenia groups." (PMID 29872072, 2018). "Based on the collective results, IL-6, SPARC, MIF and IGF-1 were selected for analysis as potential biomarkers for sarcopenia." (PMID 29872072, 2018). "Taken together, IL-6 and IGF-1 are extremely important regulators of bone and muscle metabolism, which makes them interesting targets for the treatment of osteopenia or sarcopenia." (PMID 25712618, 2015). "A recent study concluded that in the aged brain miR-29 was increased and correlates with the reduction of insulin-like growth factor-1 In our study, we found that miR-29 were increased in aged muscle of rodents and related with sarcopenia." (PMID 24659628, 2014). "Observational studies in frail elderly populations have shown a robust relationship between low circulating IGF-1 levels and sarcopenia, poor muscle strength, and physical performance." (PMID 24152751, 2013). "To confirm these observations made on humans, we studied mice overexpressing muscle-specific IGF-1, which are protected from sarcopenia." (PMID 23977392, 2013). "Several investigators have shown that skeletal muscle specific over-expression of IGF-1 is beneficial for sarcopenia." (PMID 22184279, 2011). "A number of studies have shown that there is an age-related decline in the level of muscle IGF-1 during sarcopenia." (PMID 19079548, 2008). "Another open question is the role of biomarkers of biological aging and musculoskeletal reserve, including proteomic risk scores, low IGF-1, serum myostatin, TNF-α, and vitamin D, which may help identify individuals at risk for sarcopenia and poor recovery." (PMID 40700118, 2025).
sarcopenia (continued). "Physical inactivity caused by sarcopenia may result in reduced expression and low serum levels of brain-derived neurotrophic factor (BDNF) and insulin growth factor (IGF-1), which were reported to be associated with physical inactivity." (PMID 40400912, 2025). "This study found that the IGFBP5 target may regulate the progression of fibrosis and sarcopenia in aging skeletal muscle through the IGF-1 pathway." (PMID 40144669, 2025). "The reduction of testosterone and IGF‐1 levels with age may render patients with RLS more vulnerable to sarcopenia in the geriatric population currently experiencing sleep disorders." (PMID 39568327, 2025). "However, high plasma IGF-1 levels can increase muscle mass to decrease the incidence of aging sarcopenia." (PMID 40801027, 2025). "And the research results showed that exercise may not only improve serum IGF-1 concentration in adolescents and healthy older adult people, but also may have a promoting effect on older adult populations with frailty and/or sarcopenia." (PMID 40917423, 2025). "Although acute FGF19-FGFR4/β-Klotho signaling enhances adenosine monophosphate-activated protein kinase (AMPK)-driven glucose utilization, chronic elevation induces insulin-like growth factor 1 (IGF-1) resistance that disrupts myocyte hypertrophy—a key process in sarcopenia progression." (PMID 40969368, 2025). "Meanwhile, the activation of PI3K/AKT by IGF-1 can also inhibit ubiquitin-mediated degradation of proteins and apoptosis in skeletal muscle cells, reduce necrosis of muscle tissue, and thus alleviate the development of sarcopenia and its comorbidities." (PMID 40917423, 2025). "A systematic search was conducted in PubMed, Web of Science, Cochrane Library, EMBASE and Scopus (from inception to July 2025) to identify randomized controlled trials (RCTs) investigating the impact of exercise interventions on serum IGF-1 levels in older adults with frailty and/or sarcopenia." (PMID 40917423, 2025). "Conversely, heart disease may induce sarcopenia through inflammation, insulin-like growth factor-1, angiotensin, sex hormones, myostatin, physical inactivity, and malnutrition." (PMID 41440545, 2025). "IGF-1 levels were significantly lower in patients with cirrhosis or sarcopenia." (PMID 39624154, 2025). "Therefore, increasing IGF-1 levels is considered a potential strategy for preventing and treating sarcopenia." (PMID 41140691, 2025). "However, the clinical utility of IGF-1 as a biomarker remains under investigation, especially in the context of sarcopenia." (PMID 40944148, 2025). "However, it should be noted that current evidence for BFRT-induced hormonal responses (e.g., GH, IGF-1, testosterone) in elderly populations with sarcopenia remains limited, with most studies conducted in healthy older adults or younger individuals." (PMID 40926887, 2025). "For example, in primary sarcopenia, ST detects IGF1 downregulation in Type I fibers together with DST, GATM, and PLIN4 upregulation in Type II fibers, indicating parallel anabolic failure in slow fibers and stress-induced cytoskeletal and metabolic remodeling in fast fibers." (PMID 40718353, 2025). "A systematic review of biomarkers in patients with hip fractures identified decreased IGF-1 concentrations as one of the characteristic changes in individuals with sarcopenia, making IGF-1 a potential component of biomarker panels for the clinical assessment of muscle function." (PMID 41303670, 2025). "It was reported that female subjects with sarcopenia had significantly lower serum IGF‐1 levels." (PMID 40713933, 2025). "Further investigations into the limb muscles of aged mice and humans are required to confirm whether combined treatment with androgens and IGF1 could be effective in treating muscle atrophy conditions such as sarcopenia." (PMID 39292748, 2024). "Therefore, the activation of the IGF‐1/Akt/mTOR pathway in muscles plays an important role in ameliorating sarcopenia by promoting muscle protein synthesis." (PMID 39513373, 2024).
sarcopenia (continued). "In the early stages of sarcopenia, there may exist some mechanism that stimulates the production of IGF-1, contributing to a temporary increase in IGF levels in an effort to maintain normal muscle mass and strength." (PMID 39507055, 2024). "Disturbed sleep may reduce growth hormone, insulin-like growth factor-1, and sex hormone secretion, which in turn enhance muscle proteolysis, thus leading to sarcopenia and frailty." (PMID 39764189, 2024). "The regulation of muscle anabolism and catabolism by IGF1 and myostatin as well as inflammation have proven to be promising targets to protect from sarcopenia in general, and novel drug developments in these areas should be applied to pre-clinical models of CKD." (PMID 38791164, 2024). "Using data from 1026 Japanese women and men aged 85–89 years, a recent cross‐sectional study indicated a negative association between serum IGF‐1 level and risk of osteoporosis and sarcopenia." (PMID 38332659, 2024). "However, physical activity remains essential for reducing sarcopenia by regulating pro-inflammatory cytokines and miRNA levels through the IGF-1/AKT/mTOR signalling pathway." (PMID 38398071, 2024). "Additionally, inflammation indirectly diminishes the concentrations of growth hormone and insulin-like growth factor-1 (IGF-1), thereby adversely impacting skeletal muscle and fostering sarcopenia development." (PMID 39224122, 2024). "Thus, proper activation of the IGF‐1/Akt/mTOR pathway plays an important role in preventing sarcopenia and maintaining muscle health." (PMID 39513373, 2024). "Previous studies on the mechanisms of sarcopenia have already revealed that changes in hormone levels play an essential role and that components of the endocrine system, such as IGF-1, growth hormone (GH), as well as androgens, are the most important regulators of muscle metabolism and muscle mass." (PMID 39507055, 2024). "Furthermore, an exercise intervention trial involving elderly obese women with sarcopenia revealed a significant elevation in IGF-1 levels following a 12-week circuit training program." (PMID 39507055, 2024). "For example, an increasing number of studies indicate that interfering with the IGF-1 pathway can increasing protein synthesis, which may improve sarcopenia." (PMID 36819699, 2023). "It has been shown that sarcopenia is associated with a higher level of systemic inflammation and a lower level of anabolic hormones indicated by an increase in Tumor Necrosis Factor-Alpha (TNF-α) and a decrease in IGF-1 in elderly humans (≥60 years)." (PMID 38132107, 2023). "In addition, we found that HES ameliorated the sarcopenia by regulating AKT/mammalian target of rapamycin/forkhead box 3a signaling through an increase in insulin-like growth factor (IGF)-1 expression in the old mice." (PMID 37566094, 2023). "Circulating IGF-1 levels are lower in sarcopenic subjects than in non-sarcopenic subjects, and its levels are associated with sarcopenia in the elderly as well as fat mass and the prevalence of comorbidities in obese subjects." (PMID 37237929, 2023). "In an animal model, NAFLD is reported to be associated with decreased muscle mass and strength as well as decreased IGF-1 levels, suggesting that decreased IGF-1 may contribute to the development of NAFLD-related sarcopenia." (PMID 37424859, 2023). "Therefore, the prevailing view is that IGF-1 decreases in obese people with sarcopenia, while it increases with exercise, especially resistance training." (PMID 35250869, 2022). "Indeed, patients with sarcopenia have been reported to have lower GH and IGF-1 levels, with the severity of sarcopenia associated with reduced serum IGF-1." (PMID 35665221, 2022). "In addition, patients in the sarcopenia group had lower IGF-1 levels but higher myostatin and HOMA-IR levels than the nonsarcopenia group." (PMID 35371569, 2022).
sarcopenia (continued). "The present study aimed to clarify whether the serum IGF-1 level, which has been reported to be related to sarcopenia and frailty, is related to the LS." (PMID 35948948, 2022). "Plasma IGF-1 decreases with age, which implies a risk for the development of sarcopenia since there is a hypothesis that low IGF-1 is a possible biomarker for sarcopenia." (PMID 36362238, 2022). "As shown in topic 4.5.2, IGF-1 is also a hepatokine, in which a lack of it can imply a risk for the development of sarcopenia by the mechanism of muscle hypertrophy and atrophy inhibition." (PMID 36362238, 2022). "The anabolic properties of GH suggest that the manipulation of the GH/IGF-1 axis may provide a possible therapeutic option for the treatment of many of the adverse changes which occur with ageing and in particular sarcopenia." (PMID 33816477, 2021). "In elderly European men aged ≥70 years, low baseline IGF-1 was related to a greater reduction in gait speed; however, it is necessary to identify whether the replacement of IGF-1 is effective and safe to reverse sarcopenia in randomized controlled studies." (PMID 33803020, 2021). "Sarcopenia (AWGS criteria) in the older population was associated with GH and IGF-1." (PMID 34943268, 2021). "Anabolic resistance in aging individuals may be due to the changes in systemic anabolic hormones with increasing age (e.g., testosterone and IGF-1), which has a direct correlation with the onset of sarcopenia." (PMID 33816540, 2021). "Because reduced insulin/IGF1 signalling leads to lifespan extension in worms and hypomorphic mutants of the insulin/IGF1-like receptor daf-2 show increased healthspan including a delay in the onset of sarcopenia, we decided to use this model." (PMID 34723324, 2021). "Physical inactivity resulting from sarcopenia may also decrease the expression of insulin-like growth factor-1 (IGF-1) and brain-derived neurotrophic factor (BDNF) which are known to be modulating factors for brain neuroplasticity." (PMID 32076075, 2020). "The important positive effect of IGF-1 on muscle mass was demonstrated in humans including community-dwelling middle-aged and elderly adults, and IGF-1 is considered as a promising therapeutic agent for sarcopenia resulted from aging or hypogonadism and muscle weakness from staving." (PMID 32256674, 2020). "It has been suggested that the age-related decline in IGF-1 and GH levels could play a role in the development of sarcopenia, while chronic physical exercise may boost GH-IGF-1 axis activity." (PMID 31963330, 2020). "Therefore, serum IGF-1 levels were low in patients with sarcopenia, and low IGF-1 levels result in the progression of HCC." (PMID 33028209, 2020). "Furthermore, these findings suggest that changes in oxidative stress, HCY, and IGF-1 and the anthropometric indicators including height, weight, and BMI, as well as the life habit (education, smoking, and drinking) could be the risk factors and diagnostic marker of sarcopenia in the TDM elderly." (PMID 33381601, 2020). "Moreover, IGF-1 levels decrease with age and are regarded as a potential mediator of sarcopenia or frailty." (PMID 31581569, 2019). "Finally, sex steroids and IGF-1 are essential for bone and muscle metabolic regulation and, indeed, the role of sex hormones in the pathogenesis of sarcopenia and osteoporosis has been well documented." (PMID 31068903, 2019). "In addition, the modulation of PGC‐1α, by IGF‐1Ea and IGF‐1Eb isoforms, emerges as a key aspect of the ability of the two IGF‐1 isoforms to counter sarcopenia." (PMID 30953403, 2019). "The mTORC1 regulators TSC were also phosphorylated in IGF-1 treated -/-inositol cell lines compared to control which suggests IP6K1 could be implicated in Akt-mTORC1 signaling and therefore sarcopenia." (PMID 31552262, 2019).